CXCL10 (C-X-C motif chemokine ligand 10)
Diseases named in the same sentence as CXCL10 in open-access papers (continued):
Sharing a sentence is not in itself a finding about the gene and the disease.
infection (continued). "For example, infection of human embryonic neural progenitor cells with JCPyV resulted in significant upregulation of the cytokines/chemokines such as CCL5/RANTES, GRO, CXCL1/GROα, CXCL16, CXCL8/IL-8, CXCL5/ENA78, and CXCL10/IP-10 and the chemokine receptor CXCR2." (PMID 31408949, 2019). "After infection with lymphocytic choriomeningitis virus, CXCR3 deletion leads to impaired production and localization of effector CD8+ T cells, and CXCL10 precisely coordinates effector CD8+ T cells to the site of Toxoplasma gondii, another intracellular eukaryotic pathogen." (PMID 31440475, 2019). "During infection of primary human cortical astrocytes, for example, cytomegalovirus induces release of chemoattractant protein-1 and IL-8, while human immunodeficiency virus (HIV) induces release of IL-6 and Zika virus induces release of CXCL-10, IL-6, IL-8, IL-12, and RANTES." (PMID 30442152, 2018). "With the exception of CXCL10 (IP10) and interferon-stimulated gene 20 kDa protein (ISG20), both of which are dually regulated by IFN-α/β and IFN-γ, low-level ISG induction is restricted to the first weeks of infection and subsides before peak HAV RNA abundance in the liver." (PMID 30174659, 2018). "Severe IV infection induces many cytokines; IFNαβ, TNFα, IFNγ, C-X-C motif chemokine (CXCL) 10 (CXCL10), CXCL9, C-C motif ligand (CCL) 2 (CCL2), CCL4, CCL5 and interleukin (IL)−6 (IL-6), IL-2, IL-8, and IL-10 have all be observed to be upregulated during severe IV infection in humans." (PMID 30250466, 2018). "Furthermore, because the changes in CXCL10 levels were more significant than those in IFN-γ levels, CXCL10 could be a more useful biomarker to screen the infection stages of TB." (PMID 28752079, 2017). "But, infection of lentivirus containing the N-terminal fragment of iOPN could not increase or restore SeV-induced expression of IFN-β, CXCL10, Mx1 and CCL5 in WT and OPN-deficient macrophages, respectively." (PMID 27026194, 2016). "The levels of inflammatory cytokines and chemokines, i.e., IL-6, TNF-α, CCL3/MIP-1α, CXCL1/KC, and CXCL10/IP-10, which have been reported to contribute to lung pathology, also decreased in BALF from Mint3−/− mice compared to those from WT mice on day 4 after infection." (PMID 27883071, 2016). "The results revealed that only CXCL10 was specifically and significantly elevated in the HEP-Flury or NDV pre-infected mice, suggesting that CXCL10 may play a role in blockage of early CVS-11 infection of the CNS." (PMID 27242764, 2016). "In vitro infection of cultured adipocytes with T. cruzi revealed that a panel of proinflammatory cytokines was upregulated; these include IL-1β, IFN-γ, TNF-α, chemokine ligand (CCL2), CCL5, and C-X-C motif chemokine 10 (CXCL10) The expressions of TLR-2 and 9 are also upregulated." (PMID 25276058, 2014). "In addition, 1,25(OH)2D treatment enhanced secretion of CXCL8 (p<0.03) and CXCL10 (p<0.03) production, either in the presence or absence of infection." (PMID 24475177, 2014). "Infection with both low and high virulence isolates resulted in down-regulation of mRNA levels for chemokines CCL2, CCL3L, CXCL2 and chemokine receptors CCR1, CCR5, CXCR3, CXCR4 and up-regulation in expression of mRNAs for CCL4, CXCL10 and chemokine receptor CCR7." (PMID 23265239, 2013). "CXCL10 is an interferon inducible gene and in our studies the increase in CXCL10 might be explained by the enhanced levels of IFN-γ in the lungs of immunized and infected mice at the same timepoint after infection." (PMID 24086140, 2013). "Since CXCL10 is induced by type I and type II IFNs the higher mRNA levels for this chemokine in cells infected with OURT88/3 isolate may be as a consequence of increased type I IFN induction in these infections." (PMID 23265239, 2013). "In CXCL10−/− mice, PBA infection caused modest increase in HO-1 mRNA, but not in HO-1 protein [(neither in plasma nor tissue], there could be a number of reasons." (PMID 22479586, 2012).
infection (continued). "Infections of N-PRRSV viruses resulted in fever and inflammatory response, as indicated by high expression of proinflammatory cytokines and chemokines, adhesion molecules, inflammatory enzymes and receptors, such as IL-1β, IL8, SELL, ICAM, CCL2, CXCL9, CXCL10, B2M, proteasomes, cathepsins." (PMID 20614006, 2010). "Furthermore, CXCL10, along with Tumor necrosis factor-Related Apoptosis-Inducing Ligand (TRAIL) and CRP levels in the blood, forms a powerful host-derived signature for differentiating viral from bacterial infections, demonstrating a high AUC in the diagnosis and prognosis of these infections." (PMID 39861921, 2025). "This aligns with higher cellular CXCL10 mRNA expression in LNCaP cells compared to PANC-1 upon rSFV infection, supporting the hypothesis that innate non-conventional cellular pathways, such as NF-kB or IRF3 activation, play a role in SFV-induced CXCL10 expression independent of the JAK-STAT pathway." (PMID 38425844, 2024). "Additionally, upon SFV-GFP infection, LNCaP cells exhibit significantly higher expression of IFN-β and CXCL10 than PANC-1 cells, which could be explained by the elevated levels of RIG-I or TLR3 expression in LNCaP, leading to better RNA-sensing and boosting of subsequent immune responses." (PMID 38425844, 2024). "Furthermore, CXCL10 regulates the development and function of T cells, recruiting Th cells expressing the chemokine receptor CXCR3 (primarily Th1 cells), and stimulating the activation and migration of immune cells (such as NK cells, monocytes, and T cells) to sites of infection." (PMID 37964304, 2023). "Interestingly, whereas TLR4 inhibition (TAK-242, 10 μM) did not alter enhanced OAS1 and IRF7 expression in response to hypoxic priming and SARS-CoV-2 infection, it completely abolished the expression of chemokine ISGs CCL2 and CXCL10, despite the fact that the infection rate was not affected." (PMID 37377965, 2023). "It is noteworthy that CXCL10 (produced mainly by astrocytes) might have a major neuropathogenic role; for example, CXCL10-/- and CXCR3-/- mice challenged with P.berghei ANKA or T.brucei control the infection more readily and are resistant to the neurologic disorder." (PMID 36569929, 2022). "Moreover, interferon-γ-induced protein CXCL10 secreted by monocytes, endothelial cells, and fibroblasts is prominent in SARS-CoV patients and one of the early chemokines increased in blood and lung tissue with its level increasing with the rise in infection and returning to normal during recovery." (PMID 35062368, 2022). "In our study, BVDV-2 infected goat PBMCs showed increased transcription of CCL3, CCL4, CCL5, CCL20, CXCL10 and decrease of CCL2, suggesting that such chemokines may contribute to the recruitment and regulation of macrophages or other inflammatory cells to the infected sites after infection." (PMID 31226933, 2019). "Therefore, levels of CXCR3 (receptor for CXCL9 and CXCL10), CXCR5 (receptor for CXCL13), CCR5 (receptor for CCL3 and CCL5), and CCR7 (receptor for CCL19) were analyzed on CD45hiCD11bloCD19+ B cells which infiltrated the brain at 7, 14, 30, and 60 days post infection." (PMID 27207308, 2016). "CXCL10 mRNA was predicted to be the target of multiple microRNAs that are upregulated following infection, which could indicate that endogenous regulation of CXCL10 expression is required for the resolution of infection without excessive tissue damage." (PMID 26393920, 2015). "Compared to changes in IL1-Ra or CXCL-10, the pro-inflammatory cytokines arerelatively short-lived and elevated concentrations are found only soon after theonset of serious infections, which could explain why we did not detect any of theother tested pro-inflammatory cytokines." (PMID 21559444, 2011). "For the other measured cytokines, IL-1, CXCL10, IL-23, Arginase, CCL17 and IL-12p70 no significant infection- or sex-dependent differences were observed." (PMID 40794782, 2025).
infection (continued). "When measuring mRNA expression levels from BAL cells, chemokines CCL2, CCL5, CCL8, and CXCL10 and receptors CCR5 and CXCR5 were significantly upregulated only in JBNU-22-N01 infection at 7 dpi compared with the negative control." (PMID 40459260, 2025). "Although most chemokines/cytokines did not change or remained undetectable during stable infection on days 8 and 12, CXCL9, CXCL10, CXCL11, and IFN-λ1 were increasingly induced at both time points post infection." (PMID 39980752, 2025). "Infection of these cells with SeV or transfection with poly(I:C) induced transcription of IFNB and CXCL10 that was mostly lost in cells lacking HOIL-1, indicating a conserved phenotype between murine and human cells." (PMID 38001254, 2024). "Confirmatory Western blots performed on RRV- and Ro1845VP4-G446R-infected cell culture supernatants revealed increased levels of cytokines CXCL9 and CXCL10 while Ro1845 and RRVVP4-R446G infection did not." (PMID 38860860, 2024). "In their compelling paper, mice lacking CXCR3 or CXCL10 and subjected to IFN-β treatment or infection with the virus were protected from depressive-like behaviour." (PMID 38414751, 2024). "Although macrophages respond to IFN-γ by producing CXCL10, they are not substantial sources of IFN-γ, which is mostly produced by lymphocytes to recruit macrophages to infection sites." (PMID 36992463, 2023). "In contrast, BtCoV-WIV1 infections did not induce any of these responses in the two models, whereas PCoV-GX only induced IL-8, TNF-α, and CXCL-10 in airway organoids." (PMID 36786573, 2023). "Ectopic synthesis of itaconate in A549 cells, which do not physiologically express ACOD1, reduced infection-driven inflammation, and DI reduced IAV- and IFNγ-induced CXCL10 expression in murine macrophages independent of the presence of endogenous ACOD1." (PMID 35025971, 2022). "However, downregulation of host genes such as Ccl7, Ccl5 and Cxcl10 by TAT-I24 at early time-points of infection could not be reversed when infection was performed with UV-irradiated MCMV, which was not able to induce viral gene expression due to severely damaged DNA." (PMID 35806257, 2022). "In blood samples collected after the RV infection, PBMCs were more responsive to poly-IC and production of CXCL-10 (p < 0.002) and IFN-α (p < 0.001), but not CXCL-8, showed a significant time-dependent response to the RV16 infection." (PMID 36296939, 2022). "We detected elevated levels of CXCL10, although not significant, in MOPV-infected HUVEC supernatants 48 h after infection." (PMID 35337059, 2022). "Bx795 abolished the induction of type-I/III IFNs, CXCL10, and TNF due to PVSRIPO infection; induction of IL-1β, IL-6, and IL-10 was not affected." (PMID 33767151, 2021). "Attempts at siRNA transfection on hNECs yielded MUC15 knockdown in the absence of infection, but was weaker during infection due to the high levels of MUC15 expression and activation, albeit the increase of IFNβ and CXCL10 was observed." (PMID 31307416, 2019). "The induction of cytokines (IL6 and TNFα), chemokines (CCL2 and CXCL10), and IFN-I genes in primary C57BL/6 astrocytes following a TMEV-BeAn infection can be mediated by TLR3 but not TLR7 or other MyD88-mediated pathways." (PMID 30669615, 2019). "qPCR analysis indicated that knockdown of UL42 promoted HCMV- but not HSV-1-induced transcription of IFNB1, ISG56, ISG54, CXCL10, and IL6 genes at 6, 12, and 24 hr post-infection in HFFs." (PMID 31107917, 2019). "There were significant increases in the numbers of CXCL10 transcripts in primary astrocytes and SK-N-SH cells, but MCP-1 expression did not significantly change upon infection in multiple cell lines except 48 h postinoculation in SK-N-SH cells." (PMID 31289185, 2019). "IL-6, CXCL10 and TNF-α concentrations were undetectable in many of the animals regardless of infection status." (PMID 29391069, 2018).
infection (continued). "Our study is descriptive, and the key claim that the abrogated CXCR3/CXCL10 axis is DPP4-mediated and occurring at the site of infection remains circumstantial without direct confirmation." (PMID 30026741, 2018). "There was significant induction of bronchial IFN-γ, CXCL11/ITAC, CXCL10/IP10, IL-15, IL-10, TNFα and IL-5 during infection in allergic asthmatics (all P < 0.05), but not in healthy controls." (PMID 28373098, 2017). "In neither immunized macaques from E1 (available pre-infection samples: n=14) nor those from E2 (n=11) did relative expression of FAM26F, MX1 and CXCL10 before infection correlate with the extent of early viral replication." (PMID 27902344, 2016). "At 18 h and 96 h post infection (p.i.), no IFN-α, IL-6, CXCL10 or CCL2 was detected in the bronchoalveolar lavage fluid (BAL) of infected MTM−/− mice, in contrast to BAL from wt animals." (PMID 26688048, 2015). "Activated Th1 CD4 T cells and effector CD8 T cells express this receptor, and promote migration of activated CD8 T cells into non-lymphoid tissue infection sites under the influence of the chemokine ligands CXCL9 and CXCL10." (PMID 26322025, 2015). "In another study in cynomolgus macaques, increases in the synthesis of CXCL-10 and CXCL11 (I-TAC) mRNA were reported in PBMC and lymph nodes, regardless of the outcome of infection." (PMID 24421914, 2014). "By contrast, the infection of MP with LASV did not result in the transcription of chemokine genes and only CXCL10 and 11 mRNA are significantly produced." (PMID 24421914, 2014). "We found the production of Cxcl10 and Il-6 was strongly impaired in cells lacking Prkdc−/− or Xrcc5−/− during MVA infection whereas the response of these cells to infection by Newcastle disease virus (NDV, an RNA virus) remained intact." (PMID 23251783, 2012). "CXCL10 and CXCL9 were found to be significantly increased in the patients with mild and severe symptoms at 6 months following initial infection compared to the patients reporting no symptoms." (PMID 21858242, 2011). "Our preliminary analysis would confirm that infection of STAT1-/- mice with virulent WT MNV-1, can result in the induction of ISGs, even in the absence of STAT1, as we observed increased levels of CXCL10 and ISG54 at 3 days post infection." (PMID 22174679, 2011). "Mice lacking Fas or FasL showed decreased expression of CXCL10 and TNF-α at day 9 post-infection." (PMID 39339840, 2024). "Concluding, 5-month-old NSPHs are immune responsive to pro-inflammatory stimulation and SeVeGFP-infection, as demonstrated by the secretion of IL-6 and CXCL10, but do not secrete pro-inflammatory cytokines following VZVeGFP-ORF23-infection, at least not for the panel applied in this study." (PMID 39351233, 2024). "Finally, there was a group of cytokines and chemokines: TNF, IFNγ, CCL5, CXCL9, CXCL10 and CXCL13, which were early after infection elevated in the vaccinated but not detectable in the naive animals, suggesting an adaptive immune response as the trigger." (PMID 39472590, 2024). "Our data also showed no significant alterations in the mRNA expression of antiviral IFNs (namely, IFN-β1 and IFN-λ1) nor in the signature chemokine CXCL10, during the secondary H3N2 infection and the HRV-A16 re-infection as compared to their respective single infections in hNECs." (PMID 37190061, 2023). "Longer-duration Rupintrivir treatment also showed no significant alterations in mRNA expression profiles of antiviral IFNs (IFN-β1 and IFN-λ1), nor in the signature chemokine CXCL10, during secondary H3N2 infection or HRV-A16 re-infection as compared to infection of hNECs without treatment." (PMID 37190061, 2023). "Of the 21 analytes that were evaluated, 9 analytes (angiopoietin, CCL3, CCL5, CCL7, CCL12, CXCL10, and TNF-α) were significantly changed in response to infection in both non-pregnant and pregnant mice, and more robust response was, in general, noted in non-pregnant mice (p < 0.05)." (PMID 38104118, 2023).
infection (continued). "Interestingly, while SIV infection significantly increased CXCL10 and CXCL11 in the hippocampus, it did not increase CCL2 in this area, suggesting regionally specific responses to infection." (PMID 35494221, 2022). "We could detect low levels of CXCL10 in supernatants from IRF3‐KO cells, but there was no increase above baseline after infection." (PMID 35670106, 2022). "However, infection with G-614G demonstrated a significant reduction in IL-6 and IFN-β in the lower COPD airway with a trend toward inhibition of CXCL10 when compared to non-diseased individuals." (PMID 36496442, 2022). "Another study reported that human MoDC infection with HSV-1 strain 17syn+, but not strain KOS, induced increased levels of cytokine expression for IFN-α/β, IL-28, IL-29, TNF-α, and chemokines CCL5 and CXCL10 at 9 hpi, yet at 18 hpi no increase was observed." (PMID 34895058, 2021). "Infection with VSV-G-NL4.3Δenv-eGFP HIV significantly increased production of CXCL10 by both HepG2 and AD38 cells in the presence of IFN-γ/P3CSK4 but there was no increase in CXCL10 following VSV-G-NL4.3Δenv-eGFP HIV infection alone." (PMID 32898182, 2020). "Furthermore, CXCL10 expression was not induced after infection of THP-1 cGAS knock out cells, consistent with CXCL10 induction being cGAS-dependent." (PMID 33300875, 2020). "We found that the majority of CD11b+ LyChi Ly6G- CD64+ inflammatory monocytes present in the ear of VACV-infected mice at 5 days post-infection were CCR5+, the receptor for CCL4, rather than CCR2+, or positive for the receptors for CXCL13 (CXCR5) or CXCL9 and CXCL10 (CXCR3)." (PMID 31603920, 2019). "Although specific CD8+ T cells infected expressed higher levels of CXCR3 on cell surface, CD8+ T-cells from the immunized group had a higher migration index compared to specific CD8+ T cells generated only by infection, after the ex vivo stimulation with CXCL9 and CXCL10, but not with CXCL11." (PMID 31356587, 2019). "The levels of IFNα and IFNβ, cytokines with potent antiviral activity, and the IFN-inducible chemokine CXCL10, were comparable in BAL fluid isolated from A20AEC-KO and A20WT animals at different time points post-infection, suggesting that the type-I IFN response is not differentially regulated." (PMID 26815999, 2016). "Although earlier studies indicated that chemokine CXCL10 mediates infiltration of T cells into ganglia after VZV and SVV reactivation, its potential role in primary infection has not been studied." (PMID 26676825, 2016). "The induction of the chemokine genes IP-10 (CXCL10) and I-Tac (CXCL11) and of the proinflammatory cytokine gene IL-6 was observed in a genome wide mRNA microarray analysis at 48 h post HAdV-B14p1 infection, but not in HAdV-C5 infected control cultures." (PMID 26168049, 2015). "Additionally, quantitative realtime PCR was performed to validate RNA-seq data and the transcript levels of cytokines/chemokines, such as CXCL10, CXCL11, IFN-γ, TNF-α and IL-24, were all up-regulated upon H5N1 and H5N8 infection (data not shown)." (PMID 26576844, 2015). "Furthermore, resting CD4+ T cells did not produce CXCL10 in response to Sendai virus infection, whereas the IL2/PHA-activated CD4+ T cells responded to this infection in a manner similar to the IL2/PHA-activated PBMCs." (PMID 24404168, 2014). "In addition, we also measured levels of CXCL10 and CCL5, at various time points following HIV-1 pWT/BaL infection, and consistently were not able to measure induction of these cytokines (data not shown)." (PMID 23431237, 2013). "Also, similarly to neuroimmune disorders induced by the infection, most of the cases were Ab-negative and cytokine analysis in a small subgroup of cases was in favor of a robust T-cell activation, with elevated levels of CXCL10 (IP-10)." (PMID 38375477, 2024).